EGR1 (early growth response 1)
Diseases named in the same sentence as EGR1 in open-access papers (continued):
Sharing a sentence is not in itself a finding about the gene and the disease.
colorectal cancer (46 papers, 2010 to 2026). A primary or metastatic malignant neoplasm that affects the colon or rectum. "In addition, colorectal cancer has been shown to be upregulated by transcription factors such as metastasis-associated in colon cancer protein 1 (MACC1) or early growth response protein 1 (EGR1), which are involved in angiogenesis and metastasis." (PMID 32492954, 2020). "Moreover, EGR1 has been proposed to be one of the genes with increased expression early in the development of colorectal cancer and to be implicated in stem cell marker regulation." (PMID 26498686, 2015). "Regarding natural ingredients, curcumin has been shown to inhibit the activity of Egr1 in monocytes and colorectal cancer cells." (PMID 38672136, 2024). "KLF4 and EGR1 together have been implicated in inducing ATF3 transcription and subsequent apoptosis in resveratrol-treated human colorectal cancer cells." (PMID 35746681, 2022). "Sanguinarine, a benzophenanthridine alkaloid, induces apoptosis in human colorectal cancer HCT-116 cells through ROS-mediated Egr-1 activation and mitochondrial dysfunction." (PMID 35243236, 2022). "Other investigations on prostate and colorectal cancer indicated that GDF-15 promoted metastasis through cooperating with EGR1 or TGFβ-mediated EMT." (PMID 34070192, 2021). "Here, we report that nootkatone increases EGR-1 both at the protein level as well as at the transcriptional level in colorectal cancer cells, and facilitates NAG-1 promoter activity." (PMID 32928152, 2020). "Previous studies have shown that SPON2 plays an important role in Egr-1-mediated inhibition of proliferation, migration, and tube formation of vascular ECs in colorectal cancer." (PMID 30736838, 2019). "Colorectal cancer-derived exosomes promote migration of endothelial cells by activating early growth response-1 (Egr-1) via the ERK1/2 and JNK signaling pathways." (PMID 30108680, 2018). "Since EGR1 is an essential regulator of cell survival, we tested the effect of TOLE, a nonsteroidal anti-inflammatory drug (NSAID) that induced cell death in an EGR1-dependent manner in colorectal cancer cells." (PMID 29228577, 2017). "Resveratrol is able to activate Egr-1 expression in several cancers including pancreatic and colorectal cancer." (PMID 26124921, 2015). "In colorectal cancer cells, Caco-2 and HT-29, curcumin down-regulated the transcription factor, Egr1, and the expression of EGFR, thereby inhibiting colorectal cancer cell growth." (PMID 25665066, 2015). "Altogether, our findings indicate that loss of TTP in tumors occurs through silencing of EGR1 and suggests a therapeutic approach to rescue TTP expression in colorectal cancer." (PMID 26343742, 2015). "In the present study, we observed that EVs derived from SW480 human colorectal cancer cells are Egr-1-inducible stimuli in endothelial cells, HMEC-1s and HUVECs." (PMID 25502753, 2014). "Here, we provide evidence that early growth response-1 (Egr-1) activation in endothelial cells is involved in the angiogenic activity of colorectal cancer cell-derived EVs." (PMID 25502753, 2014). "We found that Egr-1 activation by colorectal cancer cell-derived EVs promoted endothelial cell migration via the ERK1/2 and JNK signaling pathways and lipid raft-mediated endocytosis." (PMID 25502753, 2014). "Egr-1 expression had been found to be either decreased or undetectable in nasopharyngeal carcinoma and colorectal carcinoma." (PMID 25029911, 2014). "The importance of EGR1/ATF3 axis in death signalling is supported by recent studies that described an EGR1 driven activation of the pro-apoptotic transcription factor ATF3 in colorectal cancer cells following treatment with anti-neoplastic substances." (PMID 21034493, 2010). "Downregulation of EGR1 contributes to the proliferation of colorectal cancer." (PMID 34235076, 2021). "ALOX5 enhances colorectal cancer cell growth while EGR1 promotes colorectal cancer." (PMID 35155565, 2021).
colorectal cancer (continued). "Interestingly, a recent study reported links of histone deacetylase inhibitor (HDACi) activity to TTP, where treatment of colorectal cancer cells with HDACi activates the EGR1 transcription factor to induce TTP and provoke growth arrest." (PMID 27825143, 2016). "Furthermore, several anti-neoplastic or chemopreventive agents have recently been shown to target EGR1 expression and EGR1 driven pathways in colorectal cancer." (PMID 21034493, 2010). "Another study also found Egr-1 upregulation at the mRNA level in early-onset colorectal cancers." (PMID 20087343, 2010). "Therefore, we hypothesize that Egr-1 regulate the expression of NGX6 gene in colorectal cancer as a tumor suppressor gene." (PMID 25029911, 2014). "This is the case for Early growth Response 1 (EGR1), a major transcription factor involved in ZFP36 transcription, which is downregulated in several cancers, including colorectal cancer or HCC." (PMID 39941720, 2025). "Apart from SP4, EGR1, ARID3A, and NKX6-1, the remaining transcription factors have been reported in colorectal cancer, which supports the importance of these candidate DEMs in the mechanism of CRC tumor." (PMID 36798788, 2023). "One report showed that there was a connection between CD133 and EGR1 and emphasized the importance of the EGR1/TCF4/CD133/LGR5 network in colorectal cancer." (PMID 29246166, 2017). "In colorectal cancer, SIOMICS predicted five shared motifs, which were similar to the motif of the TFs SP1, the CAC-binding protein, TFAP2A (AP-2), KLF6 (GBF), and EGR1 (KROX), respectively (the names in parentheses are the corresponding TRANSFAC TF names)." (PMID 28684851, 2017). "These transcription factors included EGR1, a gene involved in the intestinal response to injury, and several STAT genes, which are part of a pathway that is upregulated in colorectal cancer." (PMID 27709125, 2016). "In colorectal cancer (CRC), CNN2 was found to form a complex with YAP1 and EGR1, thus regulating EGR1 expression and promoting CRC, which could be considered as a potential therapeutic target for CRC." (PMID 37188478, 2023). "A genetic study with cell lines and immunodeficient mice showed that tumor progression in colorectal cancer is related to the overexpression of the enzyme prostaglandin synthase E, due to an increase in the EGR1 (early growth response protein 1) factor, produced by the action of prostaglandin PGF2β." (PMID 34199169, 2021). "EGR1 high expression correlates with resistance to anti-EGFR treatment in metastatic colorectal cancer patients treated with cetuximab, and silencing EGR1 expression promotes killing HCT116 colorectal cancer cells and delaying tumor growth." (PMID 33506057, 2021). "This current data provides a correlation between EGR1 and TTP loss, however direct evidence linking these two events has not been examined in colorectal cancer." (PMID 26343742, 2015). "Its transcriptional activity was regulated by MAPK effector Egr-1, which could be activated by RTK ligands or mutant HRAS, on the other hand, both LY294002 and wortmannin, inhibitors of PI3K, could efficiently down-regulate KLF5 promoter transcriptional activity in DLD-1 colorectal cancer cells." (PMID 26544730, 2015). "We found that NCOR1, NONO, and PPP1CC were more highly expressed in right-sided colorectal cancer, while CLDN4, EGR1, and ID2 were more highly expressed in left-sided colorectal cancer." (PMID 41174721, 2025).
melanoma (41 papers, 2009 to 2026). A malignant, usually aggressive tumor composed of atypical, neoplastic melanocytes. "It was reported that EGR1 expression decreases in response to MEK inhibitor treatment in several melanoma cell lines and that knockdown of EGR1 causes a reduction in viability." (PMID 41154654, 2025). "For further analyses, we selected the EGR1 expression as a potential marker of ERK hyperactivation in melanoma, as the EGR1 gene encodes a transcription factor known to act downstream of the ERK signaling pathway." (PMID 39436655, 2024). "In melanoma, EGR1 has been implicated in apoptosis, cell growth, and fibronectin matrix synthesis." (PMID 31116991, 2019). "EGR1 is a transcription factor that can have oncogenic roles in melanoma and other cancers and can support angiogenesis, but it can also enhance tumor cell apoptosis." (PMID 41514118, 2026). "Treatment with small-molecule eIF4F inhibitors disrupts the negative feedback control of MAPK signaling, leading to ERK hyperactivation and EGR1 overexpression in melanoma cells in vitro and in vivo." (PMID 39436655, 2024). "While c-Myc and c-Jun expression proved sensitive to eIF4Fi and their protein levels were downregulated in RocA-treated BRAFV600E melanoma cells, the protein levels of c-Fos and EGR1 positively correlated with increased ERK activity." (PMID 39436655, 2024). "We performed Western blot analyses to determine changes in the levels of EGR1 in a panel of three BRAFV600E melanoma cell lines (A375, COLO800, and G361)." (PMID 39436655, 2024). "The gene early growth response 1 (EGR1) was the most notable upregulated gene in melanoma, with a 3-fold increase in mRNA expression compared to primary melanocytes." (PMID 38835508, 2024). "Treatment with eIF4F inhibitors leading to ERK hyperactivation promoted overexpression of EGR1 and c-Fos, whose expression was relatively low in normally growing melanoma cells." (PMID 39436655, 2024). "For example, SLNCR1 has been shown to promote melanoma invasion and growth through its interaction with androgen receptor and EGR1." (PMID 38561355, 2024). "The results strongly supported the notion that eIF4F negatively controls ERK signaling and eIF4Fi-induced ERK hyperactivation stimulates the EGR1 promoter activity in both BRAF- and NRAS-mutated melanoma cells." (PMID 39436655, 2024). "Although galectin-7 rendered B16F1 melanoma cells resistant to apoptosis but also inhibited cancer cell motility through increased expression of early growth response protein 1 (EGR-1)." (PMID 36873388, 2023). "The knowledge that EGR1 expression is regulated by the MAPK signaling pathway prompted us to employ Trametinib, the MEK1/2 inhibitor FDA-approved compound for melanoma, as a tool to reduce EGR1-TFEB expression in TFEB-driven cancers." (PMID 36888606, 2023). "It has been shown that IGF1 promoted metastasis of melanoma cells and also promoted migration and invasion of hepatocellular carcinoma cells through upregulating the expression of EGR1." (PMID 35479581, 2022). "By in-depth analysis of the changes in the transcriptome, EGR1 was identified to play a role in melanoma plasticity." (PMID 34439267, 2021). "On the other hand, SLNCR1 can also mediate gene repression: SLNCR1 recruits AR directly to EGR1-bound chromatin, where it acts as a transcription switch and represses EGR1-inducible p21 expression, therefore promoting proliferation of melanoma cells." (PMID 34638331, 2021). "Using this as a model system for tumor cell plasticity and heterogeneity, EGR1 is determined to play an important role in melanoma progression." (PMID 34439267, 2021). "Due to the same origin of melanocytes and nerve cells, we focused on the role of EGR1 in melanoma cell plasticity and heterogeneity and indeed we found EGR1 to be increased in melanoma cell lines and tissue compared to healthy melanocytes." (PMID 34439267, 2021).
melanoma (continued). "As several studies already suggested EGR1 having a role in neuronal plasticity, this gene was of strong interest for our further analysis of melanoma cell plasticity/heterogeneity." (PMID 34439267, 2021). "We confirmed EGR1 induction in MM compared to primary melanocytes (NHEM) by qRT-PCR analysis of the EGR1 mRNA expression in seven different melanoma cell lines (A375, Mel Wei, Mel Ju, Mel Juso, Mel Im, SkMel28, and WM3211) and NHEM cultured in 2D." (PMID 34439267, 2021). "EGR1 stained tissue sections supported the relevance of this transcriptional regulator in vivo and suggested that EGR1 protein can be found in most melanoma cells, in addition, activation and nuclear translocation is of importance for metastasis." (PMID 34439267, 2021). "In our analysis of deregulated pathways also cell membrane, ruffing, cellular response to laminar fluid shear stress were observed to correlate with transcriptomic changes further supporting to concentrate on EGR1 effects in melanoma." (PMID 34439267, 2021). "In summary, increasing EGR1 mRNA and protein expression during melanoma progression are a common feature in melanoma cells." (PMID 34439267, 2021). "Incubation of biotinylated, full-length SLNCR1 with A375 melanoma cell lysate followed by streptavidin pulldown enriched AR and EGR1." (PMID 31116991, 2019). "Collectively, these data further support the conclusion that endogenous SLNCR and EGR1 directly interact in vitro and at endogenous levels in melanoma cells." (PMID 31116991, 2019). "It has been previously reported that activation of the ERK/MAP kinase in melanoma cells stimulates FN biogenesis via the early growth response-1 transcription factor (Egr-1)." (PMID 26944546, 2016). "This highlighted the importance of EGR1 in melanoma progression." (PMID 38835508, 2024). "Thereby, the role of EGR1 in controlling tumor plasticity and progression in melanoma was revealed." (PMID 34439267, 2021). "We analyzed the publicly available Affymetrix array dataset with regards to EGR1 and revealed a significant correlation of EGR1 expression with the aggressiveness of melanoma metastases (GEO Profiles: GDS3964/201694_s_at, GSE8401, p = 4.48 × 10−4 log2FC 0.7632849)." (PMID 34439267, 2021). "Next, the EGR1 protein expression was examined, using publicly available data (Proteinatlas.org), on EGR1 immunohistological stainings of healthy skin, melanoma primary tumor, or melanoma metastasis tissue, and different staining patterns were observed." (PMID 34439267, 2021). "As studies in melanoma cells could demonstrate that Rho activators (calpeptin and ilomastat) regulating actin dynamics activate EGR1 expression (Gene Expression Omnibus (GEO) Profiles: GDS5670/8108370, GSE52246), we analyzed these aspects in our setting." (PMID 34439267, 2021). "Other studies revealed that also dynamic compression can activate EGR1 transcription in 3D cultures of mouse primary chondrocytes, these effects could be responsible for EGR1 induction in 3D alginate melanoma cultures." (PMID 34439267, 2021). "Based on the molecular signatures observed in our study, this link could be relevant for EGR1 in melanoma, being further induced by 3D culturing in 0.6% (w/v) alginate and therefore enhancing the number of quiescent, stem cell-like cells." (PMID 34439267, 2021). "This is also in agreement with the known induction of EGR1 via RAF/Ras signaling in melanoma, which we could also verify by analyzing a publicly available dataset and datasets previously published by our group." (PMID 34439267, 2021).
melanoma (continued). "Our data implicate the regulatory triad of SLNCR, AR, and EGR1 in promoting oncogenesis and may help explain why men have a higher incidence of and more rapidly progressive melanomas compared with women." (PMID 31116991, 2019). "In the present study, the radioresistant melanoma cell line OCM-1 with inducible overexpression of Ras-related C3 botulinum toxin substrate 2 was established based on a radiation-inducible early growth response gene (Egr-1) promoter." (PMID 31281584, 2019). "Moreover, we found that overexpression of galectin-7 increased the resistance of melanoma cells to apoptosis while inducing de novo egr-1 expression." (PMID 23658821, 2013). "Interestingly, EGR1 belongs to a distinct group of salivary marker genes expressed in melanoma-bearing mice." (PMID 20663135, 2010). "Finally, in a murine melanoma model with xenografted A375 cells, EGR1 and OPN expression was enhanced in cells derived from metastatic melanoma compared to the parental cell line as well as in metastatic melanoma versus primary melanoma." (PMID 20663135, 2010). "Upon reaching the salivary glands, the increased NGF levels in the blood could then stimulate the increased expression of TFs such as Egr-1 leading to altered gene expression and protein profiles in the saliva of melanoma-bearing mice." (PMID 19517020, 2009). "Four additional melanoma somatic mutation hotspots (> 3 mutations) were present in the assayed regions: TERT, encoding one subunit of telomerase and known to be frequently activated by somatic promoter mutations in cancer, and three ETS-related sites (RPL13A, AP3D1 and EGR1)." (PMID 37169761, 2023). "Additionally, EGR1 is known to be induced by RAF/Ras signaling in melanoma." (PMID 34439267, 2021). "We therefore hypothesize that NGF is secreted into the circulation by the melanoma, circulates to the salivary gland where it activates the receptor-mediated signaling cascade leading to Egr-1 upregulation and induction of specific gene transcription and protein translation." (PMID 19517020, 2009). "To investigate whether the developed tumors can mediate the altered expression of TFs in the salivary glands of tumor-bearing mice, we examined the NGF/Egr1 signal pathway because Egr1 was identified as an up-regulated TF in the salivary gland of melanoma-tumor mice." (PMID 19517020, 2009). "Our RNA-seq analyses showed significant upregulation of not only EGR1 but also DUSP5 and DUSP6 expression in response to eIF4Fi in both melanoma genetic contexts." (PMID 39436655, 2024). "Here we show that AR and EGR1 bind to the long non-coding RNA SLNCR and increase melanoma proliferation through coordinated transcriptional regulation of several growth-regulatory genes." (PMID 31116991, 2019). "HGF/c-MET binding up-regulates the expression of CD44v6 in murine melanoma cells through transcriptional activation of the immediate early gene egr-1; HGF seems to induce egr-1 activation via the Ras-Erk1/2 pathway." (PMID 28536400, 2015). "In the present work, we have shown that 1) galectin-7 is rarely expressed in biopsies of malignant melanoma, 2) galectin-7 reduces the motility of B16F1 cells, and 3) galectin-7 increases the resistance of B16F1 cells to apoptosis and the expression of EGR-1." (PMID 23658821, 2013). "Recently, B-RAFV600E-dependent genes were analysed by MEK inhibition or BRAF siRNA in human melanoma cell lines, revealing regulation of the transcription factors FOSL1 and EGR1 by this pathway." (PMID 20663135, 2010). "Transfection of miR mimics of miR146a or miR125b in melanoma cell lines Mel Im or Mel Ju resulted in downregulation of EGR1, however, for miR1215b this regulation was not significant." (PMID 34439267, 2021). "Moreover, we were able to show a significant correlation of genes most strongly induced in 3D alginate, with genes induced in malignant melanoma compared to primary melanocytes, including KLF2, KLF4, and EGR1." (PMID 34439267, 2021).